RAP2A (RAP2A, member of RAS oncogene family)
Description:
Small GTP-binding protein which cycles between a GDP-bound inactive and a GTP-bound active form. In its active form interacts with and regulates several effectors including MAP4K4, MINK1 and TNIK. Part of a signaling complex composed of NEDD4, RAP2A and TNIK which regulates neuronal dendrite extension and arborization during development. More generally, it is part of several signaling cascades and regulates cytoskeletal rearrangements, cell migration, cell adhesion and cell spreading.
Synonyms: K-REV; KREV; RAP2; RbBP-30
Tractability: Small molecule: a structure with a bound ligand is known; it has a binding pocket of medium quality. Antibody: its Gene Ontology location is reachable by antibodies, with high confidence. PROTAC: UniProt records ubiquitination sites on it; ubiquitination databases record sites on it; its protein half-life has been measured.
Gene: Protein-coding gene on chromosome 13 (97,434,169 to 97,469,128, forward strand). Ensembl gene ENSG00000125249.
Subcellular location: Midbody; Cell projection, lamellipodium membrane; Golgi apparatus; Recycling endosome membrane; Lysosome
Gene Ontology:
Molecular function: G protein activity; GDP binding; GTP binding; GTPase activity; magnesium ion binding; protein binding
Biological process: actin cytoskeleton organization; establishment of protein localization; intracellular protein localization; positive regulation of cell migration; positive regulation of microvillus assembly; regulation of dendrite morphogenesis; regulation of JNK cascade; regulation of postsynaptic membrane neurotransmitter receptor levels; regulation of synapse assembly; negative regulation of cell migration; Rap protein signal transduction; signal transduction
Cellular component: endolysosome; Golgi apparatus; lamellipodium membrane; lysosome; midbody; plasma membrane; recycling endosome; recycling endosome membrane; Schaffer collateral - CA1 synapse; bounding membrane of organelle; cytoplasmic vesicle membrane; cytosol; endomembrane system; membrane
Genetic constraint (gnomAD): Loss-of-function variants: 5 observed, 15.98 expected, observed/expected ratio (o/e) 0.31, 90% interval 0.16 to 0.66. The upper end of that interval is the gene's LOEUF score, 0.66, which puts it in group 2 of 6, group 1 being the genes least tolerant of losing a copy. Missense variants: 111 observed, 256.27 expected, observed/expected ratio (o/e) 0.43, 90% interval 0.37 to 0.51. Synonymous variants: 110 observed, 103.47 expected, observed/expected ratio (o/e) 1.06, 90% interval 0.91 to 1.25.
Homologues: Orthologues: chimpanzee RAP2A (99% identical), dog RAP2A (99% identical), macaque RAP2A (99% identical), mouse Rap2a (99% identical), pig RAP2A (99% identical), rat Rap2a (99% identical), tropical clawed frog rap2a (98% identical), zebrafish rap2aa (97% identical), zebrafish rap2ab (95% identical), Caenorhabditis elegans rap-2 (69% identical). Paralogues in human: RAP2B (91% identical), RAP2C (90% identical), RAP1A (62% identical), RAP1B (62% identical), RIT1 (46% identical), HRAS (46% identical), KRAS (45% identical), RRAS (45% identical), RRAS2 (45% identical), DIRAS2 (44% identical), NRAS (44% identical), RIT2 (44% identical), and 23 more.
Diseases named in the same sentence as RAP2A in open-access papers:
RAP2A is named in the same sentence as 48 diseases in open-access papers, as found by Europe PMC text mining. Sharing a sentence is not in itself a finding about the gene and the disease. The quoted sentences say what the papers report.
glioma (9 papers, 2014 to 2025). A benign or malignant brain and spinal cord tumor that arises from glial cells (astrocytes, oligodendrocytes, ependymal cells). "For example, Nedd4-1 can induce K63-linked ubiquitination of Rap2a in glioma, leading to inhibition of GTP-Rap2a activity." (PMID 38303029, 2024). "Contrary to these, RAP2A seems to play tumor suppressor functions in glioma as its downregulation is associated with glioma progression and its inhibition in the glioma cell line reduces migration and invasion." (PMID 34235179, 2021). "RAP2A has been validated and confirmed to contribute to the childhood absence epilepsy, a specific subtype of epilepsy, and may be related with a specific glioma inducing epilepsy associated symptoms, validating our prediction of epilepsy associated genes." (PMID 28255556, 2017). "RAP2A is also known to have a tumor suppressor role in the context of glioma migration and invasion." (PMID 41313155, 2025). "Mechanistically, unedited miR-376a-5p promotes aggressive glioma growth by its ability to target Ras-Related Protein Rap-2a (RAP2A), a member of the RAS oncogene family, and the concomitant inability to target Autocrine Motility Factor Receptor (AMFR)." (PMID 34282776, 2021). "Another study found that RAP2a inhibits glioma cell migration and invasion by down-regulating p-AKT." (PMID 33365310, 2020). "A search for specific targets important in glioma cell migration found that down-regulation of RAP2A(Ras-related protein Rap-2A) and up-regulation of AMFR (autocrine motility factor receptor) expression promote in vitro migration and invasion of glioma cells." (PMID 26437436, 2015).
lung carcinoma (6 papers, 2007 to 2022). "RAP2A, as a member of the Ras superfamily, was reported to be upregulated in lung cancer and nasopharyngeal carcinoma." (PMID 34090323, 2021). "RAP2A has been reported to be upregulated in various types of human cancer, such as lung cancer and nasopharyngeal carcinoma." (PMID 34090323, 2021). "Our previous study indicated that the ectopic expression of Rap2a enhanced the migration and invasion ability of lung cancer cells." (PMID 28747626, 2017). "Our previous studies have shown that Rap2a is involved in the cell migration and invasion of lung cancer cells." (PMID 28747626, 2017). "Transwell assay indicated that the ectopic expression of Rap2a promotes lung cancer cells migration." (PMID 25248704, 2014). "In lung cancer cells, ectopic expression of RAP2A enhances the migration and invasion of the cells." (PMID 34235179, 2021). "The levels of endogenous Rap2a protein in lung cancer cells were measured by Western blot." (PMID 25248704, 2014). "To clone Rap2a cDNA, which belongs to human Rasrelated small G protein superfamily, we constructed its eukaryotic expression vector and determined its expression in lung cancer cells." (PMID 25248704, 2014). "Rap2a could be expressed in lung cancer cells efciently and promotes lung cancer cell migration." (PMID 25248704, 2014).
colorectal cancer (5 papers, 2019 to 2026). A primary or metastatic malignant neoplasm that affects the colon or rectum.
glioblastoma (4 papers, 2018 to 2025). The most malignant astrocytic tumor (WHO grade IV). "It was also demonstrated that unedited miR-376a binds to the 3’ UTR of the RAP2A mRNA transcript (coding for a protein known to suppress glioblastoma cell invasion), causing the RAP2A protein’s function to be inhibited." (PMID 30197877, 2018). "Here, we consistently find low expression levels of RAP2A, the human homolog of the Drosophila ACD regulator Rap2l, in glioblastoma (GBM) patient samples, and observe that scarce levels of RAP2A are associated with poor clinical prognosis in GBM." (PMID 41313155, 2025). "Another example, DYRK3, a dual-specificity kinase, contributes to glioblastoma malignancy, and RAP2A increases the migration and invasion of osteosarcoma cell lines." (PMID 37958718, 2023). "Additionally, we show that restitution of RAP2A in GBM neurosphere cultures increases the ACD of glioblastoma stem cells (GSCs), decreasing their proliferation and expression of stem cell markers." (PMID 41313155, 2025). "RAP2A is highly downregulated in glioblastoma (GBM) patients." (PMID 41313155, 2025). "However, when miR-367a* remains unedited, it no longer targets the AMFR and instead targets RAP2A mRNA, a suppressor of cell invasiveness in glioblastoma, promoting glioblastoma invasiveness ⁠." (PMID 38785511, 2024).
renal cell carcinoma (4 papers, 2017 to 2022). "RAP2A expression was dramatically increased in renal cell carcinoma tissues compared with normal renal tissues, and the ectopic expression of RAP2A enhanced the migration and invasive ability of cancer cells through an AKT-dependent mechanism." (PMID 32194636, 2020). "RAP2A expression is increased in renal cell carcinoma tissues compared with normal renal tissues, and ectopic expression of RAP2A enhanced the migration and invasive ability of renal cell carcinoma cells at least by promoting the phosphorylation level of AKT." (PMID 32194636, 2020). "Combined with the oncogenic role of RAP2A in tumor cells, including renal cell carcinoma and thyroid cancer, we thus speculated that RAP2A was the downstream regulator involved in the miR-33a-5p negative regulation of PDAC cell functions." (PMID 34090323, 2021).
follicular thyroid cancer (3 papers, 2011 to 2022). "Upregulation of RAP2A has been observed in several human malignancies such as follicular thyroid cancer, prostate cancer, renal cancer, gastric cancer and bladder cancer." (PMID 34235179, 2021).
gastric cancer (3 papers, 2021 to 2023). A primary or metastatic malignant neoplasm involving the stomach. "In gastric cancer, the role of RAP2A was also observed in drug resistance where expression of RAP2A increased the viability, migration, and metastasis of cells by suppressing apoptosis and DNA damage." (PMID 34235179, 2021). "The objective of this study is to explore the effects of microRNA-33a-5p (miR-33a-5p)-ras-related protein Rap-2a (RAP2A) on biological functions of gastric cancer (GC) and to find the potential functional mechanism." (PMID 36046374, 2022).
hepatocellular carcinoma (3 papers, 2019 to 2021). A malignant tumor that arises from hepatocytes. "A number of studies reported that SEMA3F, UCK2, NOL10, RAP2A, ZIC2 and SAC3D1 are associated with prognosis and tumour immune infiltration in hepatocellular carcinomas." (PMID 34760691, 2021). "Results of the current study indicate that in hepatocellular carcinoma, RAP2A may act as an important oncogene and its mRNA expression is strongly associated with patient prognosis in HCC." (PMID 34235179, 2021). "HPA analysis of protein expression showed that PRDX6, GCLM, HTATIP2, NOL10, KIF18A, RAP2A and GDI2 were highly expressed in the hepatocellular carcinoma tissues compared with normal control tissues." (PMID 34760691, 2021).
Obesity (3 papers, 2022 to 2025). Accumulation of substantial excess body fat. "However, our data suggests that genetic regulation of RAP2A expression may putatively cause obesity by altering exosome mediated process." (PMID 40671801, 2025). "To determine the relevance of EPAC/RAP2A signaling in human obesity, we performed linear regression analysis on microarray data from abdominal subcutaneous adipose tissue of 56 women with or without obesity." (PMID 34847077, 2022). "RAP2A can also activate atypical MAPKs, such as TNIK, MINK, and MAP4K4, stimulating JNK and other downstream kinases, suggesting that RAP2A may have functions beyond desensitization of the β3-AR in healthy adipocytes and in the context of obesity." (PMID 34847077, 2022). "Because RAP2A and TRIB1 levels are increased with obesity in mice and humans, the basal activity of the G protein may drive Trib1 induction and subsequent downregulation of β3-AR in vivo." (PMID 34847077, 2022).
pancreatic cancer (3 papers, 2021 to 2024). "Subsequently, we searched the online Oncomine database to investigate the expression pattern of RAP2A in pancreatic cancer." (PMID 34090323, 2021).
prostate carcinoma (3 papers, 2021 to 2024). A carcinoma that arises from epithelial cells of the prostate gland. "In prostate cancer cells, RAP2A promotes androgen hypersensitivity and cell growth." (PMID 34235179, 2021).
Bladder Cancer (2 papers, 2020 to 2021). "The proliferation and invasion of cells were repressed by miR-3127 through directly targeting the 3′-UTR of RAP2A and associated with poor overall survival in bladder cancer patients." (PMID 34235179, 2021). "In bladder cancer cells, the expression of RAP2a was found significantly higher as compared to normal cells." (PMID 34235179, 2021).
liver cancer (2 papers, 2023 to 2024). An epithelial or non-epithelial malignant neoplasm that arises from the liver. "Javid and Dilshad evaluated the anticancer activity of bio-synthesized silver nanoparticles using Artemisia carvifolia extract against liver cancer, with a target on the Rap2A gene." (PMID 39458783, 2024). "The Artemisia carvifolia Buch plant extract and respective silver nanoparticles were found effective drug candidates for liver cancer targeting the Rap2A gene." (PMID 38057542, 2023). "The present study aimed to evaluate Artemisia carvifolia Buch extract and its silver nanoparticles against liver cancer targeting the Rap2A gene." (PMID 38057542, 2023). "In the current study, Rap2A protein a member of Ras Gtpase was selected as a drug target for liver cancer which has been identified as an oncogene in different types of tumors." (PMID 38057542, 2023). "In the proposed study, we observed the effect of Artemisia carvifolia Buch extract and its silver nanoparticles on the Rap2A gene for countering liver cancer progression." (PMID 38057542, 2023). "Rap2A gene expression was found to be downregulated in liver cancer cell line after treatment with silver nanoparticles and plant extract." (PMID 38057542, 2023). "Thus, the current study also provides evidences for using Rap2A gene as potential drug target for treatment of liver cancer." (PMID 38057542, 2023).
renal carcinoma (2 papers, 2017 to 2021). A carcinoma arising from the epithelium of the renal parenchyma or the renal pelvis. "In renal cancer, overexpression of RAP2A enhances the protein levels of p-Akt and promotes migration and invasion of cells by increasing p-Akt expression." (PMID 34235179, 2021). "In vivo studies also showed that Rap2a positively regulated metastasis of renal cancer cells and the expression of p-Akt." (PMID 28747626, 2017).
adenoma (1 paper, 2011). A neoplasm arising from the epithelium. "The quantitative real-time PCR analysis revealed a significant change in 3 genes: PSCK2 (a 22.4-fold decrease, P = 2.81E − 2), PLAB (an 8.3-fold increase, P = 9.81E − 12), and RAP2A (a 6.3-fold increase, P = 9.13E − 10) in carcinoma compared with adenoma." (PMID 22046576, 2011).
depression (1 paper, 2019). "Our results show that typical Rap proteins, Rap2b and Rap2a, were upregulated in the CUMS hippocampus, which indicates synaptic weakening and synaptic plasticity disturbances in depression." (PMID 31191638, 2019).
hepatoblastoma (1 paper, 2022). Hepatoblastoma (HB) is a malignant hepatic tumor and is the most common pediatric liver cancer. "However, the expression of RAP2A in GC has not been reported, except for one study that detected high expression of Rap2A in human hepatoblastoma HepG2 cells." (PMID 36046374, 2022).
laminopathies (1 paper, 2012). "We examined the effect of mutant TMEM43 on mRNA expression of four genes, LMO7, KCTD12, MBNL2 and RAP2A, located on chromosome 13, that have been shown to have abnormal expression in the setting of laminopathies with striated muscle dysfunction." (PMID 22458570, 2012).
lung fibrosis (1 paper, 2026). "Here, using a bleomycin-induced experimental lung fibrosis model, we observed that RAP2A expression was markedly upregulated in pulmonary endothelial cells and correlated with disease severity." (PMID 41671391, 2026). "Collectively, our findings identify endothelial RAP2A as a regulator of inflammatory endothelial activation in experimental lung fibrosis and suggest that targeting RAP2A-mediated signaling may represent a potential strategy to modulate endothelial-immune crosstalk during fibrotic lung injury." (PMID 41671391, 2026).
lung injury (1 paper, 2026). "Ras-related protein Rap2a (RAP2A), a small GTPase implicated in stress and inflammatory signaling, has not been systematically investigated in pulmonary endothelial cells during fibrotic lung injury." (PMID 41671391, 2026).
lymph node metastasis (1 paper, 2017). "We investigated whether Rap2a expression correlated with clinicopathological features, such as depth of invasion-pT status, lymph node metastasis-pN status and TNM stage." (PMID 28747626, 2017).
periodontitis (1 paper, 2024). An acute or chronic inflammatory process that affects the tissues that surround and support the teeth. "The integration of GWAS with the expression quantitative trait locis of these genes from the peripheral blood genetically prioritized 6 candidate genes, including 2 risk genes (RAP2A, MCUR1) and 4 protective genes (WNK1, NFIX, FOS, PANX1) in periodontitis-related T2D." (PMID 38811930, 2024). "Furthermore, RAP2A may participate in the pathogenesis of periodontitis-related T2D by regulating NK cells, as it was highly expressed in NK cells of patients with two diseases." (PMID 38811930, 2024). "The integration of GWAS with the eQTLs of these genes from the peripheral blood prioritized 6 genes, including MCUR1, RAP2A, FOS, PANX1, NFIX and WNK1, in the pathogenesis of periodontitis-related T2D." (PMID 38811930, 2024). "MCUR1, RAP2A, FOS, PANX1, NFIX and WNK1 may play important roles in the pathogenesis of periodontitis-related T2D, shedding light on the development of potential drug targets." (PMID 38811930, 2024). "Furthermore, MCUR1, RAP2A, FOS, PANX1, NFIX and WNK1 were verified to play important roles in the pathogenesis of periodontitis-related T2D, shedding light on the discovery of potential drug targets for periodontitis patients to prevent T2D." (PMID 38811930, 2024).
thyroid tumor (1 paper, 2011). A benign or malignant neoplasm affecting the thyroid gland. "Expression of PCSK2 was equally low, PLAB was equally high, whereas RAP2A expression was significantly higher (25.9-fold, P = 0.039) in microdissected carcinoma cells that have invaded through the thyroid capsule and entered blood vessels than in thyroid tumor cells growing under the capsule." (PMID 22046576, 2011).